ALDH1A1 (aldehyde dehydrogenase 1 family member A1)
Diseases named in the same sentence as ALDH1A1 in open-access papers (continued):
Sharing a sentence is not in itself a finding about the gene and the disease.
ovarian carcinoma (continued). "In addition to being OP-resistant, ALDH1A1+ ovarian cancer cells have also been found to be resistant to taxane and platinum treatments and to reacquire sensitivity after ALDH1A1 downregulation." (PMID 26064420, 2015). "Interestingly, involvement in the DNA damage response was recently identified as a function of ALDH1A1 in breast, prostate and ovary cancer cells." (PMID 25868979, 2015). "Together these data suggest that ovarian cancer stem-like cells may maintain therapeutic resistance by expressing ALDH1A1 and depletion of which, abrogates G1 and S-phase checkpoints leading to replication stress." (PMID 25216266, 2014). "Our studies also demonstrated that ALDH1A1 plays a key role in maintenance of ovarian cancer stem-like cells’ properties and might mediate carboplatin resistance through altered regulation of cell cycle and DNA repair networks." (PMID 25216266, 2014). "Importantly, our data also implicates a novel connection between ALDH1A1 status and altered regulation of cell cycle and DNA repair networks that influences on ovarian cancer stem-like cell properties and platinum resistance." (PMID 25216266, 2014). "ALDH1A1-knockdown induced DNA damage, evidenced by robust induction of γ-H2AX and BAX mediated apoptosis, with significant increases in BRCA1 expression, suggesting ALDH1A1-dependent regulation of cell cycle checkpoints and DNA repair networks in ovarian cancer stem-like cells." (PMID 25216266, 2014). "In summary, we demonstrated that ALDH1A1 facilitates the production of RA, which activates the transcription of POLQ via binding to the RAR at the RARE in the promoter region of the POLQ gene, thereby enhancing MMEJ and leading to PARPi resistance in HR-deficient ovarian cancer cells." (PMID 37429899, 2023). "ALDH1A1 regulation of senescence could be significant because the standard-of-care treatment for ovarian cancer includes platinum-based chemotherapy, and carboplatin has been shown to induce senescent cells in ovarian cancer tumors." (PMID 35884498, 2022). "Additionally, this may be true for other human cancers, as significant PXR expression levels have been detected in prostate, breast and ovarian cancers, where Aldefluor activity and ALDH1A1 expression are enriched in chemo-resistant CSCs." (PMID 27448961, 2016). "Moreover, ALDH1A1 has been proposed to play a significant role in the mechanism of resistance to cyclophosphamide in human carcinoma cells, oxazaphosphorine in human malignant blood cells and platinum or taxane in human ovarian cancer cells." (PMID 22710732, 2012). "Considering these results, which demonstrate that ALDH1A1-positive ovarian cancer cells have increased tumorigenicity and higher chemoresistance, it might be predicted that ALDH1A1, particularly in a marker set, could be a possible biomarker for early detection of ovarian carcinomas." (PMID 23319948, 2012). "For example, the CD133, ALDH1A1, FZD7 enriched ovarian cancer stem cells showed platinum and adriamycin resistance and enhanced EMT properties." (PMID 40246814, 2025). "The results demonstrated that treatment with 10 μM Ivosidenib reduced the expression of ALDH1A1 and SOX2 in ovarian cancer cells compared to the DMSO control group." (PMID 40342735, 2025). "In epithelial ovarian cancer (EOC), BRD4-mediated SEs regulate the expression of a series of stem-related genes, including a significant cancer stem cell marker ALDH1A1." (PMID 39090713, 2024). "Another pan-ALDH1 inhibitor, 637A, inhibits ALDH1A1 (IC50 = 246 nM), ALDH1A2 (230 nM), and ALDH1A3 (348 nM) induced calcium-dependent necroptosis in ovarian cancer cell line A2780." (PMID 38612911, 2024). "The results showed that HMGB3 knockdown significantly impairs the spheroid forming ability of ovarian cancer cells and inhibits SOX2 and ALDH1A1 expression." (PMID 37328851, 2023). "Glypican-3, ALDH1A1, TNFR2, STAT3, FOXP3, and TIM3 are increasingly recognised biomarkers to predict chemoresistance in women with ovarian cancer." (PMID 36768291, 2023).
ovarian carcinoma (continued). "The goal of our study was to examine the role of aldehyde dehydrogenase 1A1 (ALDH1A1) expression in paclitaxel (PAC) and topotecan (TOP) resistant ovarian cancer cell lines." (PMID 35328460, 2022). "Genes significantly downregulated by ALDH1A1 inhibition included stem cell markers (CD44, FZD7, and SOX9) and genes involved in chemoresistance (ABCB1 and NFκB) in ovarian cancer." (PMID 35884498, 2022). "Elevated ALDH1A1 activity is a marker of drug-resistant cancer cells, modelled here with matched cisplatin-sensitive and -resistant human SKOV3 ovarian cancer cells." (PMID 35656483, 2022). "Previous clinical research in ovarian cancer patients indicated overexpression of SALL4 protein while conflicting expression patterns for ALDH1A1 at the protein level have been reported in ovarian cancer studies." (PMID 35090523, 2022). "This study investigated the relationship between ALDH1A1 expression and expression of drug transporters and ECM molecules in PAC- and TOP-resistant ovarian cancer cell lines." (PMID 35328460, 2022). "Other ovarian cancer stem cells (OCSCs), identified by surface markers CD44, Prominin 1 (PROM1, CD133), and Aldehyde Dehydrogenase 1 Family Member A1 (ALDH1A1), reportedly involved in EOC development, relapse, and chemoresistance." (PMID 35401749, 2022). "In taxol-resistant ovarian cancer cells, NEB along with DCDC2, ANKRD18B, ALDH1A1, and ITGBL1 were overexpressed suggesting the involvement of these AR-related genes in taxol resistance." (PMID 35975176, 2022). "PIK3R3 expression in ovarian cancer positively correlated with sex determining region Y-box 2 (SOX2), CD44, and aldehyde dehydrogenase 1 (ALDH1A1)." (PMID 35761259, 2022). "Increased expression of BRD4 in ovarian cancer cells resulted in an increase of ALDH activity, while diminished BRD4 activity decreased ALDH activity by direct suppression of ALDH1A1 gene expression." (PMID 34758842, 2021). "Cells with decreased expression of ALDH1A1 presented spontaneous DNA damage, in addition to dephosphorylation and consequent de-activation of CHK1, which contributed to chemosensitization of ovarian cancer cells." (PMID 34758842, 2021). "PI3-K inhibitors used in cisplatin-resistant ovarian cancer cell lines exhibited reduction in CD44variant6, CD117, ALDH1A1, and Snail expression." (PMID 35582216, 2020). "The second goal of this paper is to compare the relations between ALDH1A1 and PTPRK expression in development of drug resistance in ovarian cancer cell lines." (PMID 31027318, 2019). "In parallel, GPX4 expression positively correlated with elevated ALDH1A1 levels in colon CSCs 53, and fluorescence-activated cell sorting (FACS) analysis revealed that SOD2 was upregulated in ALDH+ ovarian cancer cells." (PMID 31695757, 2019). "Previously, we observed an ALDH1A1 CSCs-like population in PAC- and TOP-resistant ovarian cancer cell lines." (PMID 31412536, 2019). "To ascertain the role of DDB2 in the regulation of ALDH1A1 expression, we overexpressed DDB2 in ovarian cancer cell lines possessing low DDB2 expression, or downregulated DDB2 in ovarian cancer cell lines possessing high DDB2 expression." (PMID 29752431, 2018). "Our experimental system, ALDH1A1-high (ALDH-H) subpopulation, was isolated and stabilized using doxorubicin-resistant ovarian cancer A2780 cells." (PMID 30166520, 2018). "A similar observation was made by others, where the presence of ALDH1A1 positive cells was demonstrated in A2780 CIS-resistant and SKOV-3 taxane-resistant ovarian cancer cell lines." (PMID 30583585, 2018). "DDB2 can inhibit the ovarian cancer cell dedifferentiation through downregulation of ALDH1A1; a selective ALDH1A1 inhibitor is able to reduce the tumorigenic CSC subpopulation and halt tumor growth in ovarian cancer cells possessing low levels of DDB2." (PMID 29752431, 2018).
ovarian carcinoma (continued). "Additional role of ALDH1A1 is its regulatory function on ATP-binding cassette (ABC) drug transporters, which in turn leads to the resistance of ovarian cancer to chemotherapeutics." (PMID 29552329, 2018). "Taken together, these data indicate that inhibition of ALDH1A1 activity is able to reduce the CSC subpopulation, particularly in the ovarian cancer cell population with low DDB2 expression." (PMID 29752431, 2018). "This represents the study where molecules related with CSCs (ALDH1A1) and ECM (LOX, collagens) models of drug resistance are described as occurring simultaneously in ovarian cancer cells treated with PAC and TOP." (PMID 30583585, 2018). "As can be seen, the expression of ALDH1A1 and ALDH2 vary in different cancers, as well as between ovarian cancer PTC and TSC." (PMID 29552329, 2018). "For example, ALDH1A1 expression has been reported to correlate with increased in vitro clonogenic activity in NSCLC, esophageal cancer, ovarian cancer, pancreatic cancer, and renal cancer." (PMID 26445849, 2016). "Furthermore, it has been reported that ALDH1A1 contributes to enhanced DNA repair and a poly ADP-ribose polymerase inhibitor (PARPi) resistance in ovarian cancer cells by inducing ATRA production and activating its associated signaling pathway." (PMID 41303640, 2025). "Interestingly, AhRR and PPP1R3C expression significantly correlates with stemness markers’ (ALDH1A1, CD44, ABCG2, NANOG) expressions in ovarian cancer tissues (p < 0.01)." (PMID 37511212, 2023). "Therefore, this study aimed to retrospectively investigate the expression of ALDH1A1, CD133, and CD44 in primary epithelial ovarian cancer samples." (PMID 36768723, 2023). "In the ovarian cancer tissues, further significant positive correlations were observed between DAB2 and CSC markers (CD34, ALDH1A1, CD117 (Kit)) and mesenchymal markers (MMP9, SNAI1 and MMP3) and negative correlations with mesenchymal markers (CDH2, FOXC2 and SOX10)." (PMID 37815603, 2023). "Targeting ALDH1A1 in combination with chemotherapy could block senescence and inhibit CSC enrichment to overcome resistance and improve outcomes for ovarian cancer patients." (PMID 35884498, 2022). "We investigated the specific ALDH1A1 inhibitors, NCT-505 and NCT-506, that were previously developed and tested on ovarian cancer cell lines and were shown to sensitize paclitaxel-resistant ovarian cancer cells." (PMID 35372040, 2022). "Thus, we also detected the expression difference of several ovarian cancer stem cell markers, including CD44v6, CD117, aldehyde dehydrogenase 1 family member A1 (ALDH1A1), and Snail, between EOC-cis and parental cells." (PMID 31234823, 2019). "In the current study, we were interested in whether ALDH1A1-positive cells could also be present and related to DOX and MTX resistance of ovarian cancer cell lines." (PMID 31412536, 2019). "The immunohistochemical analysis of ovarian cancer tissues in this experiment also revealed the subpopulation of cells with noticeable strong ALDH1A1 signal found among surrounding ALDH1A1 negative cancer cells." (PMID 30583585, 2018). "The role of ALDH1A1 in ovarian cancer stem cells, although it is not fully clear, is not far from its nominal role, i.e. its detoxifying role in terms of preventing the accumulation of reactive oxygen species and of reactive aldehydes." (PMID 29552329, 2018). "It was hypothesized that ovarian cancer is driven and sustained by cancer stem cell as shown by CD44+/CD24-, CD117 and CD133, especially ALDH1A1." (PMID 29552329, 2018). "In drug-resistant ovarian cancer cell lines, high expression of BCRP and multidrug resistance protein 1 (MDR1) was accompanied by ALDH1A1 overexpression, and the inhibition of ALDH activity reduced drug efflux transporter expression, leading to sensitization to chemotherapy." (PMID 30166520, 2018).
ovarian carcinoma (continued). "An approximate 1600-fold increase in ALDH1A1 expression was detected as well as a 3-fold increase in HOTAIR expression in ALDH1A1 positive ovarian cancer cells relative to negative cells." (PMID 28420874, 2017). "ALDH1A1 positive cells isolated from ovarian cancer cell lines are chemoresistant and significantly more tumorigenic capacity than ALDH1A1 negative cells." (PMID 27863439, 2016). "ALDH1A1 and CD133 are two well established ovarian cancer stem cell markers." (PMID 27888804, 2016). "For example, recent studies show that knockdown of aldehyde dehydrogenase 1 family, member A1 (ALDH1A1) in ovarian cell lines results in dramatic decrease of KLF4 and p21 protein levels, thereby leading to S and G2 phase accumulation in ovarian cancer stem-like cells." (PMID 27028863, 2016). "However, the expression of CDC20, SDC1 and ALDH1A1 were not significantly correlated with PFS of ovarian cancer patients (all P>0.05)." (PMID 33123295, 2020). "Enhanced ALDH1A1 expression due to DDB2 silencing-induced transcription de-repression plays a critical role in this process, and ALDH1A1 inhibition can block the non-CSC-to-CSC conversion, limit the CSC subpopulation, and halt the tumor regrowth in DDB2-downregulated ovarian cancer cells." (PMID 29752431, 2018). "Treatment with RA results in downregulation of ALDH1A1/ALDH3A1 expression or decreased ALDEFLOURTM activity, and, in one recent study it has been reported that there is a reduction of in vitro metastatic behavior and reduction of xenograft growth of ovarian cancer cells after RA treatment." (PMID 26445849, 2016). "Interestingly, BET inhibitors inhibit ALDH activity by eliminating BRD4-mediated ALDH1A1 expression through the activation of SEs and related eRNAs, offering a theoretical basis for the clinical application of JQ1 to inhibit the growth of cisplatin-treated ovarian cancer cells in vitro and in vivo." (PMID 39090713, 2024). "To determine whether the expression of these genes can be regulated by ALDH1A1, we first analyzed the microarray data in a publicly available dataset (GSE82304) that contains gene expression information in ALDH+ vs ALDH- cells isolated from an ovarian cancer cell line SKOV317." (PMID 37429899, 2023). "A small series of ALDH1A1 and ALDH1A pan-inhibitors are available, called CM10, A37 and NCT 501 hydrochloride that were deeply investigated against ovarian cancer, but that could be also useful to characterize the potential validity of ALDH1A1 as target in CRCs." (PMID 34880756, 2021). "Given that the ALDH1A1 inhibitor NCT-501 can offset DDB2 silencing-induced non-CSC-to-CSC conversions, we reasoned that inhibition of ALDH1A1 activity is also able to reduce the CSC subpopulation and diminish their tumorigenicity in ovarian cancer cells carrying a low level of DDB2." (PMID 29752431, 2018).
lung carcinoma (128 papers, 2008 to 2025). "A recent study has reported that TESC promotes the expression of ALDH1A1 in lung cancer and high expression of ALDH1A1 is associated with poor survival of PTC patients." (PMID 35173149, 2022). "A recent meta-analysis shows that increased ALDH1A1 expression is associated with poor overall survival and disease free survival in lung cancer patients." (PMID 26783961, 2016). "Finally, a recent meta-analysis revealed that increased ALDH1A1 expression is associated with poor OS and disease-free survival in lung cancer patients." (PMID 35087112, 2022). "Most significantly, since overexpression of TAZ is found in over 60% lung cancer, inhibiting TAZ or ALDH1A1 alone or in combination may provide a more effective therapy for the treatment of TAZ-associated lung cancer in the future." (PMID 28415606, 2017). "In conclusion, we found that AuO, an ingredient of incense smoke, significantly increases the metastatic abilities and stemness characters of lung tumor cells through the activation of ALDH1A1, which is known to be associated with poor outcome and progression of lung cancer." (PMID 28722353, 2017). "In erlotinib-resistant lung cancer cells, the upregulated expression of SOD2 and GPX4 induced by aldehyde dehydrogenase 1A1 (ALDH1A1) reduces the ROS-RCS levels caused by erlotinib and endows TKI resistance." (PMID 38982494, 2024). "A similar effect of garcinol on the cellular phenotype in lung cancer cells was recorded through the reduction of ALDH1A1 (Aldehyde Dehydrogenase 1 Family Member A1) expression, a cancer stem-like cell biomarker." (PMID 37373500, 2023). "Genetic knockdown or pharmacological inhibition of ALDH1A1 in lung cancer enhances oxidative stress and sensitivity to chemotherapy." (PMID 37886948, 2023). "Flow cytometry of lung cancer cell lines and patient tumors indicated elevated ALDH activity in most NSCLCs, linked to ALDH1A1 expression." (PMID 37886948, 2023). "Further findings also observed that PC9/gef cells gefitinib-resistant lung cancer cells) exhibited higher percentages of ALDH1A1 than PC9 cells (gefitinib-sensitive cells)." (PMID 35053430, 2022). "An association between ALDH1A1 and EGFR TKI resistance in lung CSCs has been investigated, wherein ALDH1A1+ lung cancer cells were found more resistant to gefitinib than the corresponding ALDH1A1− fraction." (PMID 35053430, 2022). "ALDH1A1-positive lung cancer cells were shown to exhibit resistance to gefitinib when compared to ALDH1A1-negative lung cancer cells." (PMID 35301287, 2022). "ALDH1A1 drives the maintenance of a CSC‐like subgroup of lung cancer cells and transcriptionally enhances EGF expression, promoting LUSC tumourigenesis." (PMID 36504325, 2022). "Results from a single‐cell proteomic profiling analysis revealed a higher level of CD133 compared with other stemness markers, such as NANOG and ALDH1A1, in lung cancer cells with EMT phenotypes." (PMID 36226253, 2022). "In Lu99 cells, dinactin significantly downregulated ALDH1A1, Nanog, Oct4, and Sox2 mRNA expression, which are transcription factors that are required to maintain pluripotency in lung cancer." (PMID 36551502, 2022). "siRNA-mediated knockdown or chemical inhibition of ALDH1A1 in A549 and H522 lung cancer cell lines decreased their proliferative and migratory capacities." (PMID 33550205, 2021). "This is well reflected in the lung cancer data analyzed here wherein there is an upregulation of ALDH1A1; however, with a significant downregulation of RA-responsive genes, possibly owing to the elevated levels of PRMT3." (PMID 33495566, 2021). "References showed an increase in ALDH1 activity and increase in ALDH1A1 protein level in lung cancer." (PMID 34066916, 2021). "One of the most commonly used is flow cytometry (FCM) employing CSC-specific cell surface markers, like CD133 and CD44, and the ALDH1A1, which is the most used and described marker for lung cancer stem cells." (PMID 33868998, 2021).